RN7SL246P (RNA, 7SL, cytoplasmic 246, pseudogene)
Gene: Miscellaneous RNA gene on chromosome 12 (45,874,035 to 45,874,330, forward strand). Ensembl gene ENSG00000265093.
Homologues: Orthologues: chimpanzee Metazoa_SRP (99% identical), macaque Metazoa_SRP (91% identical). Paralogues in human: RN7SL712P (82% identical), RN7SL1 (82% identical), RN7SL2 (81% identical), RN7SL3 (80% identical), RN7SL559P (80% identical), RN7SL679P (80% identical), RN7SL797P (80% identical), RN7SL664P (80% identical), RN7SL397P (79% identical), RN7SL45P (79% identical), RN7SL296P (79% identical), RN7SL630P (79% identical), and 705 more.